EMP3 (epithelial membrane protein 3 (MAM blood group))
Diseases named in the same sentence as EMP3 in open-access papers (continued):
Sharing a sentence is not in itself a finding about the gene and the disease.
glioblastoma (continued). "In addition, silencing EMP3 reduces the proliferation and migration of glioblastoma cells." (PMID 38229014, 2024). "The latest glioblastoma reports, combined with bioinformatics research and in vivo and in vitro investigations, confirmed that EMP3 was also related to GBM immunosuppression." (PMID 36217151, 2022). "Epithelial membrane protein 3 (EMP3) is a tetraspan membrane protein overexpressed in isocitrate dehydrogenase-wild-type (IDH-wt) glioblastoma (GBM)." (PMID 34067658, 2021). "Epithelial membrane protein 3 (EMP3) induced CCL2 secretion and expression of PD-L1 in glioblastoma multiforme cells and promoted the recruitment of TAMs of the M2 phenotype." (PMID 37313405, 2023). "Indeed, methylation of EMP1 and EMP2 in human cancer is rarely reported, although methylation of EMP3 was previously detected in NSCLC and glioblastoma, suggesting different gene regulatory programs in EMPs." (PMID 33799364, 2021).
breast carcinoma (20 papers, 2013 to 2026). "The genes positively associated with EMP3 expression status bear a close association with the PI3K-AKT pathway among HER2-enriched breast cancers." (PMID 42017338, 2026). "EMP 3 is upregulated in HER-2-positive breast cancer and is associated with Myc proteins, and its knockdown has been shown to reduce cell proliferation and invasiveness in hepatocellular carcinoma." (PMID 37629198, 2023). "Loss and gain of function studies have revealed that EMP3 impedes breast cancer cell S-phase entry, DNA replication, and proliferation." (PMID 34511602, 2021). "Consistently, loss and gain of function studies demonstrated that EMP3 inhibits breast cancer cell S-phage entry, DNA replication, DNA damage repair, and stem-like properties." (PMID 34511602, 2021). "Notably, EMP3 was shown to be associated with a favorable prognosis in four subtypes of breast cancer." (PMID 34511602, 2021). "Kaplan-Meier patient survival analysis in breast cancer cases revealed that EMP3 expression levels are positively correlated with patient survival." (PMID 41225146, 2025). "According to much research, EMP3 promotes breast cancer progression and is highly expressed in breast cancer." (PMID 36217151, 2022). "Taken together, these in silico analyses suggest that EMP3 functions as a tumor suppressor in breast cancer." (PMID 34511602, 2021). "EMP3 knockdown reduced expression of ATG7, phosphorylated P62, and LC3A/B-II, while EMP3 overexpression upregulated these proteins, demonstrating that EMP3 promotes breast cancer cell autophagy." (PMID 34511602, 2021). "Here EMP3 was demonstrated as a tumor suppressor in breast cancer and a target to overcome chemoresistance, as a result of the negative modulation of DNA replication, DNA damage repair, and stemness." (PMID 34511602, 2021). "EMP3 downregulates YTHDC1, a RNA-binding protein involved in m6a modification, which at least in part mediates the effects of EMP3 on breast cancer cells." (PMID 34511602, 2021). "As a negative regulator of stem-like properties, EMP3 inhibits the expansion of breast cancer stem cells." (PMID 34511602, 2021). "EMP3 expression in breast cancer cells is negatively regulated by miR-765, which can bind to the 3′-UTR of EMP3 mRNA." (PMID 31652725, 2019). "EMP3 mRNA is significantly upregulated in lymph node metastases of breast carcinomas, and is related to the levels of ErbB2 expression." (PMID 31652725, 2019). "EMP3 was up-regulated in primary breast carcinoma tissues and regulated cell proliferation and invasion in SK-BR-3 cells." (PMID 27527869, 2017). "Finally, for EMP 3, an increase in its expression is demonstrated in breast cancer, and a decrease in its expression is observed in lung cancer." (PMID 37629198, 2023). "Various studies have reached different conclusions on the role of EMP3 in breast cancer." (PMID 36217151, 2022). "find that SK-BR-3 cells exhibit remarkable proliferation and invasion inhibitory effects in vitro when EMP3 is knocked down by shRNA, which demonstrates that EMP3 could function as an oncogene in human breast cancer." (PMID 35646656, 2022). "EMP3 blocks Akt/mTOR pathway in breast cancer cells, suggesting that this pathway may mediate EMP3-induced suppression of DNA replication, cell growth, and DNA damage repair." (PMID 34511602, 2021). "Taken together, these data indicate that EMP3 is a putative tumor suppressor in breast cancer, and EMP3 downregulation may be responsible for breast cancer chemoresistance." (PMID 34511602, 2021). "Therefore, EMP3 downregulation contributes to the chemoresistance and radioresistance of breast cancers." (PMID 34511602, 2021). "EMP3 was also found to induce certain breast cancer cell growth." (PMID 34511602, 2021). "Accordingly, EMP3 sensitizes breast cancer cells to the DNA-damaging drug Adriamycin." (PMID 34511602, 2021). "EMP3 is not only a tumor suppressor but also a target to enhance chemosensitivity in breast cancer." (PMID 34511602, 2021).
breast carcinoma (continued). "EMP3 overexpression in breast cancer was related to stronger HER-2 expression that may indicate a novel therapeutic target." (PMID 33123464, 2020). "Additionally, miR-765 can regulate EMP3 in some primary breast cancer tissues." (PMID 36217151, 2022). "Intracellular signaling related to EMP3 was unknown in breast cancer." (PMID 34511602, 2021). "For example, reduced expression of epithelial membrane protein 3 (EMP3) leads to increased levels of YTHDC1, which promotes DNA repair in breast cancer cells by upregulating BRCA1 and RAD51, ultimately resulting in chemoresistance." (PMID 39095902, 2024). "One suitable example is that increased YTHDC1 mediated by epithelial membrane protein 3 (EMP3) downregulation exhibited a positive effect on the expression of BRCA1 and RAD51, thereby promoting DNA repair in breast cancer cells, leading to chemoresistance." (PMID 35843942, 2022). "Finally, the role of EMP3 in SK-BR-3 and BT474 cells which represent other subtypes of breast cancer was investigated." (PMID 34511602, 2021). "Overexpression of EMP3 is found in oligodendroglial tumors, and primary breast carcinomas without altering DNA methylation." (PMID 26472188, 2015). "Furthermore, an inverse correlation between EMP3 promoter hypermethylation and mRNA expression levels has also been demonstrated in neuroblastoma, ESCC, and breast cancer cell lines." (PMID 24083241, 2013). "However, overexpression of EMP3 is related to retain chromosomes 1p and 19q in oligodendroglial tumors, and relevant to histological grade III, lymph node metastasis, and strong Her-2 expression in primary breast carcinoma." (PMID 26472188, 2015). "The negative modulation of YTHDC1 by EMP3 and the effect of YTHDC1 overexpression on breast cancer cells together demonstrate that YTHDC1 and m6A modification at least in part mediate EMP3-induced suppression of homologous recombination repair." (PMID 34511602, 2021).
neuroblastoma (9 papers, 2013 to 2023). Neuroblastoma (NB) is the most common solid, extracranial childhood tumor. "Early studies on EMP3 showed that EMP3 CpG island hypermethylation was found to be an indication of poor prognosis in neuroblastoma patients." (PMID 37091145, 2023). "Demethylating agents can restore the EMP3 expression in neuroblastoma cells, significantly decreasing cell proliferation." (PMID 36217151, 2022). "In neuroblastoma tumors, the hypermethylation of the EMP3 gene, which leads to the EMP3 downregulation, is also closely related to the low survival rate of patients." (PMID 36217151, 2022). "EMP3 has also been reported to show frequent promoter methylation in high-grade astrocytomas and neuroblastomas, two tumor entities that display frequent allelic deletions at 19q13.3." (PMID 27801851, 2016). "Treating neuroblastoma cell lines with a demethylating agent, 5-aza-2-deoxycytidine, to restore EMP3 expression reduced colony formation density and tumor growth in nude mouse xenograft models." (PMID 26472188, 2015). "In previous studies, aberrant methylation in the promoter region of the EMP3 gene has been found to be associated with loss of heterozygosity (LOH) on 19q13.3 in both oligodendrogliomas and neuroblastomas." (PMID 24083241, 2013). "Therefore, as PCC is also a neural crest origin tumor like neuroblastoma, hypermethylation-mediated EMP 3 silencing can be expected in PCC." (PMID 37629198, 2023). "In neuroblastoma, the EMP3 gene is hypermethylated and silenced." (PMID 36217151, 2022). "Moreover, constitutive expression of EMP3 in neuroblastoma cell lines induces tumor suppressor-like features in murine xenograft models." (PMID 27527869, 2017). "However, it has been reported that EMP 3 is more frequently methylated in neuroblastoma than in PCC (methylation rate: 68.4% versus 6.1%), which could explain the retainment of EMP 3 expression in PCC." (PMID 37629198, 2023).
hepatocellular carcinoma (8 papers, 2015 to 2025). A malignant tumor that arises from hepatocytes. "To investigate the expression patterns of EMP1, EMP2, and EMP3 in hepatocellular carcinoma (HCC) and normal liver tissues, we analyzed mRNA expression data from 374 HCC patients obtained from The TCGA database." (PMID 39866225, 2025). "Nevertheless, in urothelial and hepatocellular carcinomas, EMP3 shows more potential cancer-promoting effects." (PMID 36217151, 2022). "EMP3 is significantly expressed in hepatocellular carcinoma, promoting the invasion and migration of hepatocellular carcinoma cells." (PMID 36217151, 2022). "In addition, EMP3 can promote hepatocellular carcinoma (HCC) by activating the PI3K/AKT pathway and uPA/MMP‐9 cascade, upregulation of which is closely associated with differentiation." (PMID 34268874, 2021). "EMP3 promotes tumor growth and metastasis through the PI3K/AKT pathway, and is highly expressed in upper urinary tract urothelial carcinoma (UTUC) and hepatocellular carcinoma (HCC)." (PMID 37887529, 2023).
gastric cancer (7 papers, 2019 to 2024). A primary or metastatic malignant neoplasm involving the stomach. "Low EMP3 expression has been linked to inhibiting the progression of gastric cancer, notably curtailing the migration and invasion of cancer cells." (PMID 38229014, 2024). "High EMP3 expression is associated with a worse overall survival rate [Hazard ratio (HR) = 1.71; 95% confidence interval (CI) = 1.32–2.22; p < 0.0001] and progression-free survival in gastric cancer (HR = 1.99; 95% CI = 1.45–2.72; p < 0.0001)." (PMID 36217151, 2022). "Recent research has shown EMP3 is a positive regulatory fulcrum in reversing GC cell resistance to cisplatin in gastric cancer treatment." (PMID 36217151, 2022). "In gastric cancer, EMP3 has been suggested as a downstream effector of TWIST1/2 and a regulator of EMT." (PMID 32857809, 2020). "Further, overall survival and the progression-free period are very poor in patients with gastric cancer with high levels of EMP3." (PMID 31652725, 2019). "Similar to gastric cancer, EMP3 is highly expressed in HCC and negatively correlates with the degree of tumor differentiation." (PMID 31652725, 2019). "Furthermore, high expression levels of EMP 3 are a poor prognostic factor in brain glioma, breast phyllodes tumor, gastric cancer, and urothelial carcinoma." (PMID 37629198, 2023). "In gastric cancer cells, EMP3 can act as a downstream effector of TWIST1 and TWIST2 and participate in the EMT of gastric cancer." (PMID 36217151, 2022). "EMP3 is induced by TWIST1/2 and regulates epithelial-to-mesenchymal transition of gastric cancer cells." (PMID 33799364, 2021).
urothelial carcinoma (6 papers, 2015 to 2023). A malignant neoplasm derived from the transitional epithelium of the urinary tract (urinary bladder, ureter, urethra, or renal pelvis). "EMP3 enhances the expression of integrins, particularly α1, α2, α3, α5, α6, αV, and β1, to promote the proliferation and migration of urothelial carcinoma cells." (PMID 31652725, 2019). "EMP3 promotes cancer cell proliferation and growth in urothelial carcinomas, while it is considered to be a tumor suppressor in other cancers." (PMID 29867202, 2018). "Cell proliferation and migratory activity are enhanced in urothelial carcinoma cells overexpressing EMP3, which increases signaling through the PI3K/AKT and FAK/Src pathways, leading to the activation of RhoA and ROCK1/2 and the upregulation of the expression of certain integrins." (PMID 31652725, 2019). "EMP3 and ErbB2 levels are high in high-grade urothelial carcinoma cells." (PMID 31652725, 2019). "The functional crosstalk between ErbB2 and EMP3 activated the ErbB2-PI3K-AKT pathway to promote cancer cell proliferation and migration in urothelial carcinoma." (PMID 27527869, 2017). "EMP3 belongs to the peripheral myelin protein 22-kDa (PMP22) gene family as novel therapeutic targets in human cancer, which is the most important indicator of progression-free and metastasis-free survival for patients with urothelial carcinoma of the upper urinary tract." (PMID 35492358, 2022).
astrocytomas (4 papers, 2013 to 2024). "In astrocytic tumors, the frequency of EMP3 hypermethylation was as follows: 22.2% in pilocytic astrocytomas, 33.3% in WHO grade II astrotcyomas, and 37.5% in WHO grade III astrocytomas." (PMID 24083241, 2013).
lung carcinoma (4 papers, 2009 to 2023). "However, in comparison, EMP3 might act as a tumor suppressor in esophageal carcinoma and lung cancer." (PMID 34268874, 2021). "The role of EMP3 in lung cancer has not been fully clarified and the molecular mechanism in non-small cell lung cancer need to be confirmed further." (PMID 36217151, 2022).
non-small cell lung carcinoma (4 papers, 2015 to 2023). A group of at least three distinct histological types of lung cancer, including non-small cell squamous cell carcinoma, adenocarcinoma, and large cell carcinoma. "EMP3 and EMP1 have been reported to be involved in the PI3K/Akt pathway in HCC, and in the tumorigenesis of non-small cell lung cancer." (PMID 32857809, 2020).
oligodendroglioma (4 papers, 2013 to 2024). A well-differentiated (WHO grade II), diffusely infiltrating neuroglial tumor, typically located in the cerebral hemispheres. "In oligodendrogliomas, univariate analysis by the Kaplan-Meier method revealed that EMP3 promoter hypermethylation as detected by MS-PCR correlates with a significantly longer OS (P = 0.001), also in WHO grade III tumors (P = 0.034)." (PMID 24083241, 2013). "Consistent with previous reports, oligodendrogliomas (Grade II) exhibited lower EMP3 expression compared to non-tumor, (P < 0.05." (PMID 27527869, 2017).
brain tumors (3 papers, 2021 to 2024). "In GBM, EMP3 expression is upregulated to promote the progression of brain tumors, and a high EMP3 expression is associated with poor prognosis." (PMID 37887529, 2023). "In GBM, EMP3 expression is upregulated to promote the progression of brain tumours, and high expression of EMP3 is associated with a poor prognosis." (PMID 33964937, 2021). "EMP3 expression is upregulated in brain tumors, particularly in GBM." (PMID 38229014, 2024). "However, EMP3 expression is upregulated in brain tumours, especially in GBM." (PMID 33964937, 2021).
esophageal squamous cell carcinoma (3 papers, 2013 to 2019). Esophageal squamous cell carcinoma (ESCC) is a type of esophageal carcinoma (EC) that can affect any part of the esophagus, but is usually located in the upper or middle third. "EMP3 was reported to be a tumor suppressor gene and it underwent hypermethylation-mediated transcriptional silencing in Glioma, Esophageal squamous cell carcinoma (ESCC) and Non-small cell lung cancer (NSCLC)." (PMID 31895687, 2019). "The potential tumor suppressive function of EMP3 has also been reported to be repressed in esophageal squamous cell carcinoma cell lines." (PMID 26472188, 2015).
gallbladder cancer (3 papers, 2019 to 2024). "Recently, EMP3 has been reported to suppress the progression of gallbladder cancer, and its low expression is strongly associated with poor prognosis." (PMID 31652725, 2019). "For instance, in gallbladder cancer, EMP3 inhibition activates the ERK1/2 pathway, leading to the inhibition of cell proliferation and metastasis." (PMID 39248711, 2024). "The level of miR-663a is augmented in human gallbladder cancer tissues, and knockdown of this miRNA reciprocally increases EMP3 expression." (PMID 31652725, 2019). "The inoculation of gallbladder cancer cells overexpressing EMP3 into nude mice induces significantly smaller and lower weight tumors than that of EMP3-depleted cancer cells." (PMID 31652725, 2019). "Downregulation of EMP3 in gallbladder cancer activates the MAPK/ERK signaling pathway to promote cancer progression." (PMID 31652725, 2019). "Knockdown of EMP3 protein in gallbladder cancer cells that possess high levels of endogenous EMP3 increases proliferation, while overexpression of EMP3 inhibits migratory activity and promotes high apoptotic activity by increasing the expression of caspase-3 and caspase-9." (PMID 31652725, 2019).
malignant glioma (3 papers, 2016 to 2024). A grade III or grade IV glioma arising from the central nervous system. "Analysis of the GSE7696 data revealed that PPIC, EMP3 and CHI3L1 have greater than two-fold up-regulation at the transcription level and were drastically increased in malignant gliomas when compared to non-tumor brain tissue." (PMID 27801851, 2016).
melanoma (3 papers, 2021 to 2022). A malignant, usually aggressive tumor composed of atypical, neoplastic melanocytes. "The predictive model created in this work comprises five inflammatory response-related genes: C3AR1, CXCL10, EIF2AK2, EMP3, and ICAM1, all of which are all overexpressed in melanoma tissue and are associated with a poor prognosis." (PMID 35982458, 2022). "Notably, EMP3 knockdown in melanoma C32 cells inhibited Akt phosphorylation and cell viability, indicating that the effect of EMP3 on Akt signaling and the role of EMP3 in malignancies are tumor-specific." (PMID 34511602, 2021). "Among them, only PDZD2, NPY1R and ADH1B have not been reported in melanoma studies, and EMP3 has only been reported in uveal melanoma." (PMID 35433681, 2022).
ovarian carcinoma (3 papers, 2007 to 2022). A malignant neoplasm originating from the surface ovarian epithelium. "Here, we designed small-scale siRNA screens targeting these six mesenchymal signature genes (CD99L2, EMP3, ITGA5, SYDE1, VIM, ZEB1) to explore their functional relevance and their roles during EMT reversal by nintedanib (BIBF1120) in a mesenchymal-like SKOV3 ovarian cancer cell line." (PMID 26061747, 2015). "The observed fold changes in gene expression between control (NOSE) and ovarian cancer (EOC) samples were significant (p < 0.01) for CAV 1 (-30.88) and CXCL6 (-4.22) but not significant (p < 0.06) for EMP 3 (+1.10)." (PMID 17254359, 2007).
bladder cancer (2 papers, 2015 to 2021). "These biochemical findings correlated well with increased migration of bladder cancer cells upon EMP3 overexpression." (PMID 34067658, 2021). "For example, EMP3 overexpression and knockdown in human bladder cancer cells have been shown to culminate into a concomitant increase and reduction in ErbB2/HER2 protein levels, respectively." (PMID 34067658, 2021). "Conversely, EMP3 overexpression promoted cell migration of human bladder cancer cells." (PMID 34067658, 2021). "Recently, it has been reported that ErbB2 and EMP3 reciprocally up-regulate each other accompanied with activation of PI3K/Akt pathway to promote proliferation and migration of human bladder cancer cells." (PMID 26472188, 2015).
breast phyllodes tumor (2 papers, 2020 to 2023). A benign, malignant, or borderline circumscribed biphasic neoplasm that arises from the breast. "In this study, we aimed to evaluate the expression of EMP1, EMP2, and EMP3 in breast phyllodes tumors (PTs), and to investigate their clinical implications." (PMID 32857809, 2020).